GNLY (granulysin)
Diseases named in the same sentence as GNLY in open-access papers (continued):
Sharing a sentence is not in itself a finding about the gene and the disease.
pancreatic carcinoma (1 paper, 2020). "We also demonstrated the enhanced cytotoxicity of the immunotoxin compared with granulysin alone on the pancreatic carcinoma Capan-2 cells, showing that 10 μM of SM3GRNLY induced 70% of cell death, while GRNLY did not induce more than 45%." (PMID 32859066, 2020).
Pleural effusion (1 paper, 2025). The presence of an excessive amount of fluid in the pleural cavity. "In liver metastasis BL T cells, granzyme family genes (GZMA, GZMH, and GNLY) were enriched, while pleural effusion BL T cells showed increased TFF3, AGR2, MGP, and MIF expression." (PMID 39955556, 2025).
pregnancy disorder (1 paper, 2012). A disorder that is related to pregnancy. "On the other hand, several studies have shown that granulysin may be involved in different pregnancy disorders." (PMID 21912564, 2012).
psoriatic arthritis (1 paper, 2023). Joint inflammation associated with psoriasis. "Some studies have shown that GNLY accelerates the deterioration of psoriatic arthritis and that its apoptosis-related mechanism mediates the development of joint lesions." (PMID 37152368, 2023).
synovitis (1 paper, 2024). Inflammation of a synovial membrane. "There was also a negative correlation between the density of Granulysin-positive cells and the following SLE criteria (SLICC-12): synovitis (p = 0.0466), hypocomplementemia (p = 0.0408) and anti-SM antibody (p = 0.0252)." (PMID 37783618, 2024).
T cell lymphomas (1 paper, 2018). "In the present investigation, we carried out an immunohistochemical analysis of granulysin, in normal and neoplastic lymphoid tissues, with the aim to assess its potential utility to refine the diagnosis of NK/T cell lymphoma subtypes." (PMID 30151671, 2018). "Granulysin was found to be mainly restricted to some NK/T cell lymphoma subtypes, and the highest expression was observed in ENKTLs (61/86; 71%)." (PMID 30151671, 2018).
testicular cancer (1 paper, 2026). A primary or metastatic malignant neoplasm that affects the testis. "The testicular cancer samples were grouped by the expression patterns of Copines genes, and the DEGs between groups included GNLY, MGP1, CFD2, CCL21, SPARCL13 as well as some other genes involved in the malignant progression of cancer." (PMID 40337972, 2026).
trisomy 21 (1 paper, 2024). A chromosomal disorder consisting of the presence of an extra chromosome 21. "Ontologies such as response and defense against viruses, antimicrobial humoral immune responses mediated by antimicrobial peptides, and the regulation of myoblast fusion were associated with 20 genes in the Trisomy 21 with CHDs datasets (GSE196443 and GSE217557), including GNLY, IFI44L, and CXCL9." (PMID 39596121, 2024).
tuberculoid leprosy (1 paper, 2011). A principal or polar form of leprosy in which the skin lesions are few and are sharply demarcated. "Furthermore, cytotoxic granulysin-expressing CD4+ T-cells have been isolated from skin lesions of tuberculoid leprosy patients." (PMID 21234358, 2011).
uveitis (1 paper, 2025). An inflammatory process affecting a part of or the entire uvea. "Notably, GNLY and CR1 displayed inverse regulation patterns, being upregulated in the uveitis-only group but downregulated in the systemic disease-associated uveitis group." (PMID 40270958, 2025). "Importantly, only three IRGs (CR1, CST7, and GNLY, all regulated by IFN types I and II) were differentially expressed in both uveitis groups, differing on regulation among groups." (PMID 40270958, 2025). "However, there has not been a well-established association between uveitis and CST7 or GNLY." (PMID 40270958, 2025).
varicella (1 paper, 2019). "Recently it was observed that patients with varicella displayed significantly lower levels of serum granulysin (a marker of NK cell activity) compared to healthy controls, despite maintained numbers of circulating NK cells." (PMID 31194857, 2019).
tumor (149 papers, 2004 to 2026). "A risk score was generated for each tumor sample with the expression score of GNLY, DSC1, and DLX1, and patients were categorized into two subtypes as high risk and low-risk groups." (PMID 37876438, 2023). "Granulysin has been shown to damage both the plasma and mitochondrial membranes of several tumor types by causing an influx of Ca2+ and an efflux of K+ from the cell." (PMID 34368150, 2021). "Culture of Vδ2+γδ T cells with Daudi tumour cells caused the highest concentrations of granulysin released into co‐culture supernatants." (PMID 32794189, 2020). "Activated cytotoxic T cells infiltrate into the tumor area and kill tumor cells by enhancing pore formation in the tumor cell membrane and causing subsequent secretion of death-inducing granules containing granzymes, perforin, cathepsin C, and granulysin." (PMID 37759777, 2023). "Elevated expression of granulysin is associated with favourable outcomes in various cancers; however, in MF, the granulysin is proposed to be an alarmin molecule attracting immature dendritic cells which may promote immune tolerance to the tumor." (PMID 34204115, 2021). "The first strategy is the use of immunotoxins, which combine a cytotoxic agent, such as granulysin, with an antibody as a targeting moiety to achieve tumor-specific delivery." (PMID 40691738, 2025). "Among these, GZMK+ CD8+ T cells, GZMB+ CD8+ T cells, and NK cells exhibited high levels of effector cytotoxic genes such as GZMA, GZMB, NKG7, PRF1, and GNLY, contributing significantly to anti-tumor immunity." (PMID 40149859, 2025). "Comparative ligand-receptor analysis comparing CAF subsets with key T cell populations revealed that Fib_CD74+–CD4T_FOXP3+/CD8T_GNLY+ interactions were significantly enhanced in tumor samples." (PMID 40948762, 2025). "On the one hand, tumor cell C1_EGFR+ and C2_STAT1+ directly act on CD8T_GNLY+ through the MDK–(ITGA4+ITGB1) axis and the MIF–(CD74+CXCR4) axis to promote tumor proliferation." (PMID 40948762, 2025). "As previously discussed, the 9-kDa processed form of granulysin is a cytotoxic effector molecule stored in the LGs of cytotoxic lymphocytes and has cytotoxic activity against both microbes and some tumor cells." (PMID 40691738, 2025). "Smart, biocompatible nanoparticles can be engineered to precisely deliver extracellular-acting PFPs (e.g., PRF-1 and granulysin) directly to tumor sites or to regulate the expression and activation of intracellular PFPs (e.g., GSDMs and MLKL)." (PMID 40691738, 2025). "Genes associated with increased cytotoxicity (GZMB, GNLY, PRF1), and anti-tumor activity (NKG7) were upregulated in the cytotoxic lymphocytes, including CD8 + T cells, γδ T cells, NK cells, and ILCs." (PMID 41194247, 2025). "When we compared tumor Teff 1 with normal Teff 1, we observed an increased level of GNLY, GZMB, and IFNG was accompanied by higher HAVCR2 (TIM-3)." (PMID 39454432, 2024). "An enrichment of GRB7+ and GNLY+ CD8+ T cells (cells/mm2 tumour area) was observed in tumours treated with PI3K/mTORi and PI3K/mTORi+PD1‐i compared to those treated with vehicle or PD‐1i alone." (PMID 38711203, 2024). "Immune modules also captured highly correlated inter-tissue/inter-omic features, such as granulysin (gnly) mRNA expression in tumor biopsy samples and serum CCL2 protein, which were higher in responders." (PMID 38670099, 2024). "More tumor accumulation and higher GNLY expression can partially explain the greater antitumor activity of mNK-sEV." (PMID 39075563, 2024). "Simultaneously, increased tumor accumulation and upregulated GNLY protein expression due to mNK-sEV treatment contributed to augmented tumor suppression." (PMID 39075563, 2024). "Destruction of tumor cells by cytotoxic molecules, e.g., perforin, granzymes, granulysin and Fas ligand." (PMID 37511431, 2023).
tumor (continued). "The expression of the four target genes (MDGA2, DLX1, DSC1, and GNLY) was investigated in tumor tissues and paired blood samples from 10 BLCA patients who were enrolled in the current study." (PMID 37876438, 2023). "The cytotoxic ability of the 9 kDa isoform of granulysin is thought to be responsible for the killing of tumour cells by altering the membrane permeability of the cell, which leads to an increase in intracellular calcium, thus, inducing tumour cell lysis." (PMID 37153585, 2023). "GNLY is considered as a potential alternative to antibiotics, while GzmB was found to be highly effective in limiting human tumor progression." (PMID 35300343, 2022). "CD8+ T cells develop into cytotoxic T lymphocytes (CTL) and eliminate tumor cells by releasing cytotoxic mediators, such as granzyme B (GzmB) and granulysin (Gnly)." (PMID 36387070, 2022). "The immune cytotoxic/effector genes were mainly expressed by T and NK cells, some of which were commonly up‐regulated in the inflammation and tumor regions in the Stereo‐seq slides, including GNLY, GZMA, GZMB, and NKG7." (PMID 35986392, 2022). "There was overexpression of GNLY (cytolytic protein secreted to kill tumor cells by activated T cells and NK cells), NKG7, and CCL5 and co-expression of CD3 and GNLY (cytotoxic phenotype)." (PMID 35163329, 2022). "Remarkably, the antitumor activity of granulysin was associated with a massive NK cell infiltration, suggesting a possible immunogenic effect of granulysin-induced tumor cell death." (PMID 35740244, 2022). "Except for SPP1+TAMs, all TAMs associated with tumor progression were enriched in dMMR, while GNLY+ Monolike Macros with the anti-tumor immune function were abundant in pMMR." (PMID 36232318, 2022). "In previous studies by our group, the anti-tumor capacity of recombinant granulysin was demonstrated, both in vitro and in vivo." (PMID 35955839, 2022). "Since the expression of the Tn antigen is observed in a much wider variety of tumor types, targeting this antigen would expand the possible therapeutic applications of granulysin-based immunotoxins." (PMID 35740244, 2022). "The results indicated that ARHGAP29 expression was significantly higher in tumor samples, while GNLY and NRIP1expression was significantly lower in UCEC samples." (PMID 36568182, 2022). "GNLY functions as a lytic molecule to carry out lysis or apoptosis product in target cells, including tumor cells or cells infected by pathogens." (PMID 33842346, 2021). "GrB and additional cytotoxic effector proteins including granulysin are important mediators of the effector function of Vδ2 γδ T cells to lyse Plasmodium falciparum parasites and tumor cells." (PMID 34315922, 2021). "Granulysin has cytotoxic activity against tumor cells and other microorganisms by which it influences the negatively charged cell membranes mediated by the positive charge of granulysin." (PMID 34299145, 2021). "The efficacy of the intra-tumor injection of recombinant granulysin was demonstrated in several in vivo models of tumor development in athymic mice." (PMID 34829955, 2021). "It is well-known that CD8+ T cells can release perforin, granzymes, and granulysin to kill tumor cells, and CD4+ T cells play crucial roles in the regulation of adaptive immunity." (PMID 34262026, 2021). "Ya-Wen reported that the serum level of GNLY was negatively correlated with the proliferation of transplanted tumor cells in HIS mice." (PMID 33842346, 2021). "Although its main function is antimicrobial, acting directly on bacteria and parasites, it has been demonstrated that recombinant granulysin is also able to induce the apoptotic death of tumor cells." (PMID 34829955, 2021). "The exosomal protein levels of PFN, GzmA, GzmB, and GNLY are deciding factors for the tumor lysis ability of NK-EVs." (PMID 33808645, 2021).
tumor (continued). "These cells display important effector functions after recognizing dysfunctional somatic cells such as tumor cells, and release the cytotoxins perforin, granzyme, and granulysin." (PMID 34041030, 2021). "After stimulation, the percentage of C02-Activated-IFNG and C06-Activated-IL2RA of TCR-TMART-1 was downregulated, while the fragment of C01-Activated-CD69, C11-Activated-IL15, and C12-Cytotoxic-GNLY was upregulated with increased tumor PD-L1 levels." (PMID 33754038, 2021). "Our group was the pioneer in the characterization of the molecular mechanism by which recombinant granulysin induces the death of tumor cells, demonstrating that it fundamentally induces apoptosis in various tumor cells of hematopoietic origin." (PMID 32859066, 2020). "In this paper, we show that Vδ2+γδ T cells are capable of secreting granulysin in response to tumour." (PMID 32794189, 2020). "Expression of membrane receptors such as FCGR3A and CX3CR1, and cytotoxic genes like GZMB, FGFBP2, PRF1, and GNLY increased gradually during this transition, implying a gradually acquired tumor-killing ability in CD56dim NK cells." (PMID 33298893, 2020). "Nonetheless, the relevance of defective or decreased granulysin levels in tumor evasion to immune elimination merits future investigation." (PMID 32466293, 2020). "We also demonstrated that the antitumor action of granulysin was accompanied by a massive infiltration of NK cells in the tumor, providing evidence of immunogenicity, as well as the absence of side effects." (PMID 32859066, 2020). "In this paper, we present evidence that Vδ2+γδ T cells express granulysin intracellularly in a constitutive manner, and release this molecule on culture with the tumour cell lines Daudi and Raji, albeit to differing degrees." (PMID 32794189, 2020). "In all these experimental approaches, recombinant granulysin was injected intratumorally when the tumor was already detectable." (PMID 32859066, 2020). "Taken together, these data suggest that Vδ2+γδ T cells are activated by tumour cells, subsequently resulting in degranulation, granulysin release and cell death." (PMID 32794189, 2020). "We demonstrated that the immunotoxin targeted granulysin against the HeLa-CEA tumor after systemic injection in nude mice xenotransplanted with this tumor." (PMID 32859066, 2020). "CD8+ along with granulysin positivity in TILs constitutes additional support for the robust antitumor immune response provided by cytotoxic CD8+ tumor-infiltrating lymphocytes." (PMID 32707930, 2020). "We next designed experiments to investigate the release of granulysin from Vδ2+γδ T cells following culture with tumour cells." (PMID 32794189, 2020). "One mechanism for NK cells to induce tumor- or virus-infected target cell death involves granule exocytosis, with the direct release of cytolytic granules containing perforin, granzymes and granulysin that kill target cells via apoptosis." (PMID 31817971, 2019). "This suggests that the expression of granulysin is mainly restricted to NK cells and derived neoplasms." (PMID 30151671, 2018). "The intensity of granulysin in the 61 positive ENKTLs was strong and comparable to that of the other cytotoxic markers, and in each case, more than 75% of tumour cells were positive (score 3)." (PMID 30151671, 2018). "In our studies, we demonstrated that HIS mouse expressed GNLY and its presence suppressed the growth of both CL1-5 and HT29 tumor cells as evident by the increased expression of GNLY within the tumor mass." (PMID 29137359, 2017). "The serum level of GNLY was negatively correlated with the proliferation of transplanted tumor cells in HIS mice." (PMID 29137359, 2017). "Together these observations suggested that GNLY was produced by human CTLs and NK cells and GNLY mediated anti-tumor effects via the induction of caspase-dependent apoptosis in HIS mice." (PMID 29137359, 2017). "GNLY exhibits a broad spectrum of antimicrobial activities and potent cytotoxic action against tumor cells." (PMID 29137359, 2017).
tumor (continued). "Immunohistochemical analysis of the tumor samples demonstrated that a more intense GNLY staining in HIS mice than ones in control mice." (PMID 29137359, 2017). "The recombinant 9 kDa granulysin has been shown to kill a variety of microbes such as bacteria, fungi, yeast, parasites and several tumor cell lines." (PMID 27276051, 2016). "The 9 kDa granulysin is cytotoxic to tumor cells through the apoptotic pathway by the release of cytochrome c and apoptosis-inducing factor (AIF), and also by activation of caspases and endonucleases." (PMID 27276051, 2016). "These granules contain perforin, granzymes, granulysin and other effector molecules involved in the anti-tumor potency, as well as some unidentified components." (PMID 26309426, 2015). "The granules in the cytoplasm of CTL contain perforin, granzymes, granulysin and other effector molecules involved in the anti-tumor effect, as well as certain unidentified components." (PMID 25060707, 2014). "Interaction of the Fc with the FcγR activates effector cells, resulting in the release of molecules contained in cytotoxic granules, such as perforin, granulysin and granzymes, which leads to lysis of tumor cells." (PMID 23936189, 2013). "Statistically significant differences were observed in the distribution of perforin and GNLY expression in different stages of tumors classified according to Dukes', indicating that the percentage of total perforin and GNLY was significantly diminished in accordance with tumor progression." (PMID 42075662, 2026). "In tumor specimens, the proportion of CD4T_FOXP3+ Tregs rose, whereas CD8T_GNLY+ cells declined." (PMID 40948762, 2025). "Likewise, CTLs execute the lysis of target cells by releasing cytotoxic factors: perforins, which create pores in the membranes of (tumor) target cells, and granzymes and granulysin, which activate the caspase pathway, inducing apoptosis." (PMID 41383591, 2025). "Likewise, CD8+ T cells, or cytotoxic T lymphocytes (CTLs) execute the lysis of target cells by releasing cytotoxic factors (perforins, and granzymes and granulysin) or by the interaction of the of the FasL with Fas, inducing apoptosis of tumor cells." (PMID 41383591, 2025). "Human GNLY is initially present as a 15 kDa protein which is later cleaved to generate a 9 kDa molecule, which enables cytotoxic immune cells to directly induce cell death including tumor cells." (PMID 39643914, 2024). "In addition, 15 kDa GNLY precursor can be truncated to its 9 kDa active form after entering tumor cells to function." (PMID 39075563, 2024). "Using isolated tumor tissue, we analyzed gene expression related to cytotoxicity (Perforin, Granzyme B, Granulysin, and FasL), inflammatory or chemotactic cytokines (IFN-γ, CXCL9, CXCL10, and CXCL11), and CD8+ T cell activation and proliferation (CD69, Tbx21, IL-2, and IL-12b)." (PMID 39066478, 2024). "C5,6,7_CD8, which was predominantly composed of CD8+ T cells from tumor tissue and blood, exhibited high gene accessibility of cytotoxic molecules including GNLY, PRF1 and GZMB, with cells in C6_CD8 exhibiting the highest accessibility for these cytolytic molecules." (PMID 35668194, 2022). "Compared to ZA-expanded Vδ2+ cells, HKBCG-expanded cells tended to release more cytolytic molecules including granzymes and granulysin in response to tumour cell co-culture, whereas ZA-expanded Vδ2+ cells tended toward relatively higher levels of Th2-associated cytokines." (PMID 35404420, 2022). "The intra-tumor administration of GRNLY in these models correlated with apoptosis induction in the tumor tissue and with prominent NK cell infiltration into the tumor mass, indicating that granulysin-induced tumor cell death in vivo could be immunogenic." (PMID 35955839, 2022). "Importantly, the majority of cells in cluster 5 were from P-LN and tumor 3, and they exhibited high expression of GNLY, CD69, and GZMA, indicating that they were closely related to immune cells." (PMID 36569924, 2022).